SLC2A5 (solute carrier family 2 member 5)
Description:
Functions as a fructose transporter that has only low activity with other monosaccharides. Can mediate the uptake of 2-deoxyglucose, but with low efficiency. Essential for fructose uptake in the small intestine (By similarity). Plays a role in the regulation of salt uptake and blood pressure in response to dietary fructose (By similarity). Required for the development of high blood pressure in response to high dietary fructose intake (By similarity).
Synonyms: GLUT-5; GLUT5
Tractability: Antibody: UniProt places it where antibodies can reach, with high confidence; its Gene Ontology location is reachable by antibodies, with high confidence; UniProt predicts a signal peptide or a membrane-spanning region; the Human Protein Atlas places it where antibodies can reach. PROTAC: ubiquitination databases record sites on it; its protein half-life has been measured.
Target class: SLC superfamily of solute carriers; Electrochemical transporter; SLC02 family of hexose and sugar alcohol transporters; Transporter
Gene: Protein-coding gene on chromosome 1 (9,035,106 to 9,088,478, reverse strand). Ensembl gene ENSG00000142583.
Subcellular location: Apical cell membrane; Cell membrane; Cell membrane, sarcolemma
Subcellular location (Human Protein Atlas): Plasma membrane; Mid piece; Principal piece
Pathways (Reactome):
Digestion and absorption: Intestinal hexose absorption
Immune System: Neutrophil degranulation
Gene Ontology:
Molecular function: fructose transmembrane transporter activity; protein binding; D-glucose transmembrane transporter activity; fructose binding; transmembrane transporter activity
Biological process: fructose import across plasma membrane; fructose transmembrane transport; carbohydrate metabolic process; cellular response to fructose stimulus; D-glucose transmembrane transport; dehydroascorbic acid transport; intestinal hexose absorption; regulation of systemic arterial blood pressure mediated by a chemical signal; response to fructose; transmembrane transport
Cellular component: extracellular exosome; plasma membrane; apical plasma membrane; sarcolemma; specific granule membrane; membrane
Genetic constraint (gnomAD): Loss-of-function variants: 52 observed, 45.14 expected, observed/expected ratio (o/e) 1.15, 90% interval 0.92 to 1.45. The upper end of that interval is the gene's LOEUF score, 1.45, which puts it in group 5 of 6, group 1 being the genes least tolerant of losing a copy. Missense variants: 563 observed, 651.34 expected, observed/expected ratio (o/e) 0.86, 90% interval 0.81 to 0.93. Synonymous variants: 267 observed, 276.74 expected, observed/expected ratio (o/e) 0.96, 90% interval 0.87 to 1.07.
Homologues: Orthologues: chimpanzee SLC2A5 (99% identical), macaque SLC2A5 (97% identical), pig SLC2A5 (84% identical), mouse Slc2a5 (83% identical), guinea pig SLC2A5 (80% identical), dog SLC2A5 (79% identical), rat Slc2a5 (79% identical), zebrafish slc2a5 (67% identical), tropical clawed frog slc2a5 (63% identical), Drosophila melanogaster sut1 (33% identical), Drosophila melanogaster CG7882 (30% identical), Drosophila melanogaster sut2 (27% identical), and 31 more. Paralogues in human: SLC2A7 (59% identical), SLC2A9 (44% identical), SLC2A4 (41% identical), SLC2A1 (41% identical), SLC2A2 (39% identical), SLC2A11 (39% identical), SLC2A3 (39% identical), SLC2A14 (37% identical), SLC2A13 (29% identical), SLC2A10 (25% identical), SLC2A8 (25% identical), SLC2A6 (24% identical), and 1 more.
Diseases named in the same sentence as SLC2A5 in open-access papers:
SLC2A5 is named in the same sentence as 99 diseases in open-access papers, as found by Europe PMC text mining. Sharing a sentence is not in itself a finding about the gene and the disease. The quoted sentences say what the papers report.
breast cancer (30 papers, 2010 to 2025). A primary or metastatic malignant neoplasm involving the breast. "In addition, the SLC2A5 gene and its encodingGLUT5 are upregulated in malignant tumors such as prostate cancer, breast cancer, acutemyeloid leukemia and clear cell renal cell carcinoma and promote tumor progression." (PMID 37674366, 2023). "We also used CRISPR/Cas9 gene editing to silence the SLC2A5 gene in HeLa cervical cancer cells and in breast cancer MDA-MB-231 cells." (PMID 36268513, 2022). "According to recent reports, SLC2A5 is involved in the progression of a variety of cancers, including pancreatic cancer, breast cancer, small intestine carcinoma, and LUAD." (PMID 34604392, 2021). "Previous studies consistently approved that the expression of SLC2A5 was upregulated in several types of human cancers such as breast cancer, lung cancer, renal cell carcinoma and glioma." (PMID 34188196, 2021). "Moreover, higher mRNA expression of SLC2A5 and SLC2A12 significantly associated with worse prognosis of breast cancer patients (HR: 1.46 [1.18–1.82];p = 6E-04 and HR: 1.55 [1.12–2.14];p = 0.008, respectively)." (PMID 34488531, 2021). "SLC2A5 expression is higher in metastatic liver lesions than in normal liver; and elevated in primary lung tumors; as well as in brain, colon, testis, and uterine cancers, including breast carcinoma cell lines." (PMID 36268513, 2022).
glioma (14 papers, 2019 to 2025). A benign or malignant brain and spinal cord tumor that arises from glial cells (astrocytes, oligodendrocytes, ependymal cells). "(a) The log-fold change expression of SGmic genes (P2ry13, P2ry12, Gpr34, Slc2a5, Siglec-H, Olfml3, Tmem119, Fcrls) in glioma-associated microglia isolated from experimental RCAS tumors compared to microglia isolated from healthy control brains is shown." (PMID 30764877, 2019). "(b) The log-fold change expression of SGmic genes (P2ry13, P2ry12, Gpr34, Slc2a5, Siglec-H, Olfml3, Tmem119, Fcrls) in glioma-associated microglia isolated from RCAS tumors compared to microglia isolated from healthy control brains is shown." (PMID 30764877, 2019). "(c) Graph shows the log-fold change expression of SGmic genes (P2ry13, P2ry12, Gpr34, Slc2a5, Siglec-H, Olfml3, Tmem119, Fcrls) in glioma-associated microglia isolated from GL261 tumors as compared to microglia isolated from healthy control brains." (PMID 30764877, 2019).
lung adenocarcinoma (12 papers, 2018 to 2025). A carcinoma that arises from the lung and is characterized by the presence of malignant glandular epithelial cells. "Lung cancers with mutations in SLC2A5 promote lung adenocarcinoma cell growth and metastasis by enhancing fructose utilization." (PMID 33391440, 2021). "Notwithstanding, SLC2A5 was overexpressed in lung adenocarcinoma and the expression was associated with prognosis, it is uncertain if lung adenocarcinoma cells utilize fructose as alternative nutrient." (PMID 29531835, 2018). "SLC2A5, which promotes lung adenocarcinoma cell growth and metastasis by enhancing fructose utilization, was proven to be overexpressed in LUAD, and the expression was associated with prognosis." (PMID 35757722, 2022). "Another study showed that SLC2A5 is significantly upregulated in lung adenocarcinoma patients and overexpression of SLC2A5 determines fructose uptake and utilization efficacy and is highly correlated with poor patient survival." (PMID 32733884, 2020). "Microarray data from Oncomine and extracted from GSE31210 also supported SLC2A5 was significantly elevated in lung adenocarcinoma and SCC." (PMID 29531835, 2018). "In this study, we showed that SLC2A5 is significantly upregulated in lung adenocarcinoma patients and overexpression of SLC2A5 is highly correlated with poor patient survival." (PMID 29531835, 2018). "RNA-Seq data from TCGA revealed expression of SLC2A5 was higher in both lung adenocarcinoma and squamous cell carcinoma (SCC) compared to normal lung tissue." (PMID 29531835, 2018). "For example, as the literature shows, SLC2A5 could inhibit the development of human normal adjacent lung adenocarcinoma cytoplasmic pre-B cells." (PMID 34604392, 2021). "However, some studies have reported that FGF2 was up-regulated in thyroid cancer and SLC2A5 was up-regulated in lung adenocarcinoma, which was inconsistent with our results may be due to the different cancer type and genetic background." (PMID 37980162, 2023). "These evidences prove that when the expression of SLC2A5 increases, the body may regulate some biological processes by affecting the expression of positive and negative related genes, thus affecting the condition of patients with lung adenocarcinoma." (PMID 34604392, 2021). "In this study, we found that SLC2A5 is significantly upregulated in lung adenocarcinoma (LUAD) patients and overexpression of SLC2A5 is highly correlated with poor prognosis of LUAD patients." (PMID 29531835, 2018). "Our results showed that neither the commonest tumor-driver genes nor fructose significantly influenced SLC2A5 expression in lung adenocarcinoma." (PMID 29531835, 2018).
diabetes (11 papers, 2014 to 2023). "SLC2A1, SLC2A2 and SLC2A5 gene expression in mid-jejunal mucosa was measured to investigate whether intestinal glucose transporters could be influenced by diabetes, diet and/or metformin-pioglitazone medication and as such have an effect on the postprandial plasma glucose concentrations." (PMID 34669714, 2021).
lung carcinoma (11 papers, 2018 to 2025). "SLC2A5 promotes cell growth and metastasis in lung cancer, where hypoxia is generally associated with disease progression and poor prognosis." (PMID 34282207, 2021). "Increased expression of SLC2A5 has been associated with disease progression, increased metastasis, and an unfavorable prognosis of several types of cancers including cervical cancer, renal carcinoma, lung carcinoma, hepatocellular carcinoma, endometrial cancer cells, and pancreatic cancer." (PMID 36268513, 2022). "With regard to genes negatively associated with SLC2A5, a previous study showed that overexpression of TOB1 significantly inhibited the proliferation and metastasis of lung cancer cells." (PMID 34604392, 2021). "SLC2A5 is an oncogene and up-regulated in some cancers, that is, lung cancer and acute myeloid leukemia." (PMID 34676211, 2021). "In conclusion, this study provides comprehensive evidence for the value of SLC2A5 in lung cancer progression and its potential as a biological target and prognostic predictor of LUAD." (PMID 34604392, 2021). "Nonetheless, the regulation of SLC2A5 in lung cancer is still unknown." (PMID 29531835, 2018). "However, compared to the primary tumor, lung cancer metastases have higher levels of SLC2A3 and SLC2A5, highlighting their significance in tumor metastasis." (PMID 36518662, 2022). "Our preliminary analysis showed that the expression of SLC2A5 was upregulated in non-small-cell lung cancer (NSCLC) samples compared to normal lung tissue, but the implication of SLC2A5 upregulation in lung cancer was largely unknown." (PMID 29531835, 2018). "However, the regulation of SLC2A5 in lung cancer has not been fully elucidated, especially when hypoxia is involved." (PMID 35757722, 2022). "The expression of SLC2A5 is reported to be regulated by many factors such as substrate level, tumor hypoxia, oncogene, inflammatory factor TNF-α, and hormone levels (insulin, thyroxine, etc.)in other tumors, but its modulation in lung cancer remain unknown." (PMID 29531835, 2018).
Obesity (11 papers, 2012 to 2025). Accumulation of substantial excess body fat. "First, we identified gene sets related to the function of each obesity-related serum factor: HG/HI (Insr, Irs1, Rps6kb1, Slc2a4, Slc2a5, Slc2a1), TNF-α (Tnfrsf1a, Tradd, Traf2, Fadd), IL-6 (Il6ra, Il6st, Jak1), and fatty acids (PA, LA, Chol; Ffar1, Ffar4, Ppara, Pdk4, Pgc1a)." (PMID 37047207, 2023).
acute myeloid leukemia (10 papers, 2017 to 2025). Acute myeloid leukemia (AML) is a group of neoplasms arising from precursor cells committed to the myeloid cell-line differentiation. "Acute myeloid leukemia (AML) is metabolically characterized by SLC2A5-mediated high fructose utilization, which correlates with patient prognosis." (PMID 40549205, 2025). "A study reported that acute myeloid leukemia (AML) cells express high levels of SLC2A5 and consume fructose and use it to maintain viability, especially when glucose is scarce." (PMID 32733884, 2020). "A study on acute myeloid leukemia (AML) showed that SLC2A5 upregulation occurs in AML, and blocking the pharmacological process of SLC2A5 regulating fructose uptake could improve the phenotype of leukemia." (PMID 34604392, 2021).
colon carcinoma (10 papers, 2012 to 2026). "This is in agreement with previous reports that although fructose is the main inducer of SLC2A5 gene expression, glucose also increases SLC2A5 promoter activity, mRNA expression, and GLUT5 protein expression in the human colon cancer cell line." (PMID 34884473, 2021). "A recent study showed that a histone deacetylase inhibitor, trichostatin A, which induces SNAI1 and SNAI2 expression, inhibits SLC2A5/GLUT5 expression and thereby sensitizes colon cancer cells to cisplatin and oxaliplatin." (PMID 39458997, 2024).
type 2 diabetes (8 papers, 2010 to 2024). "SLC2A5 expression is induced in the intestine and skeletal muscle of patients with type 2 diabetes and in certain cancers dependent on fructose metabolism." (PMID 35240026, 2022).
colorectal cancer (6 papers, 2021 to 2023). A primary or metastatic malignant neoplasm that affects the colon or rectum. "However, the function and molecular mechanism of SLC2A5 in colorectal cancer (CRC) remain unknown." (PMID 34188196, 2021).
metabolic syndrome (5 papers, 2013 to 2023). A cluster of metabolic risk factors for CARDIOVASCULAR DISEASES and TYPE 2 DIABETES MELLITUS. "SLC2A5 (GLUT5-encoded) is the leading fructose absorption transporter in the kidneys, small intestine, and proximal tubules, and its overexpression causes metabolic syndrome by increasing fructose intake." (PMID 35370963, 2022). "In conclusion, this exploratory study detected some potentially interesting associations between polymorphisms of SLC2A2 and SLC2A5 with various aspects of the metabolic syndrome in the study population of PEAR." (PMID 23341889, 2013).
ovarian carcinoma (5 papers, 2021 to 2025). A malignant neoplasm originating from the surface ovarian epithelium. "Our results show that ADIRF, SLC2A5, C3orf86, HSPA1B are among the most significant PCa biomarkers, while MTRNR2L1, EEPD1, TEPP and VN1R2 are jointly important biomarkers across prostate, breast and ovarian cancers." (PMID 34001952, 2021).
pancreatic cancer (5 papers, 2017 to 2025). "SLC2A5 can increase the flux of pentose phosphate pathway and protein synthesis by increasing fructose synthesis, thus promoting the growth of pancreatic cancer." (PMID 34604392, 2021).
colitis (4 papers, 2022 to 2024). Inflammation of the colon. "In a recent study, SLC2A5+/+ and SLC2A5–/– mice fed with a 15Kcal% fructose diet were found to exhibit more severe DSS-induced experimental colitis." (PMID 37674366, 2023).
fructose intolerance (4 papers, 2015 to 2023). "Molecular analysis of genomic DNA included (I) exclusion of 3 main ALDOB gene variants causing hereditary fructose intolerance and (II) sequencing analysis of SLC2A5 gene comprising complete coding region, at least 20 bp of adjacent intronic regions and 700 bp of proximal promoter." (PMID 35387598, 2022). "While role of ALDOB-related gene variants for hereditary fructose intolerance is well established, contribution of gene variants for acquired fructose malabsorption (e.g. SLC2A5, GLUT5) is not well understood." (PMID 35387598, 2022). "As for the more recent selective event at SLC2A5, it is worth noting that some degree of fructose intolerance is widespread in humans, and fructose absorption is increased by the coingestion of glucose and is reduced by the presence of sorbitol." (PMID 26319403, 2015).
leukemia (4 papers, 2020 to 2024). A malignant (clonal) hematologic disorder, involving hematopoietic stem cells and characterized by the presence of primitive or atypical myeloid or lymphoid cells in the bone marrow and the blood. "Upregulation of the gene SLC2A5, encoding the fructose transporter protein GLUT5, results in increased fructose uptake, compensating for the relative fructose deficiency of tumor cells, thereby promoting leukemia cell survival." (PMID 38966636, 2024).
cognitive defects (2 papers, 2024 to 2025). "This was mediated via the high affinity fructose transporter SLC2A5 (GLUT5), as its deletion in neonates completely reversed microglia dysfunction and cognitive defects." (PMID 39575254, 2024).
non-small cell lung carcinoma (2 papers, 2018). A group of at least three distinct histological types of lung cancer, including non-small cell squamous cell carcinoma, adenocarcinoma, and large cell carcinoma. "Our recent data in Cell Death and Discovery show that the expression of SLC2A5 is upregulated in non-small cell lung cancer (NSCLC) samples compared to normal lung tissue." (PMID 29748554, 2018).
pancreatic ductal adenocarcinoma (2 papers, 2022 to 2024). An infiltrating adenocarcinoma that arises from the epithelial cells of the pancreas. "To test directly if deletion of the SLC2A5 gene impacts cancer progression and migration, we used CRISPR/Cas9 gene editing to inactivate the SLC2A5 gene in a highly metastatic pancreatic ductal adenocarcinoma MIA-PaCa-2 cell line, and fibrosarcoma HT1080tdT cells." (PMID 36268513, 2022).
colorectal tumour (1 paper, 2021). "Collectively, these findings suggested that SLC2A5 expression is upregulated in colorectal tumour tissues." (PMID 34188196, 2021). "We found that SLC2A5 was upregulated in colorectal tumour tissues." (PMID 34188196, 2021).
COVID-19 (1 paper, 2025). A disease caused by infection with severe acute respiratory syndrome coronavirus 2. "Further, based on results from this study and the COVID-19 host genetics initiative and its update, we further highlight several other genes of interest for our COVID-19 severity hypothesis, namely BCL11A, SLC22A31, SLC6A20, SLC2A5 and HBBP1." (PMID 40240424, 2025).
fibrosarcoma (1 paper, 2022). A malignant mesenchymal fibroblastic neoplasm affecting the soft tissue and bone. "Inhibition of SLC2A5 limits HT1080tdT fibrosarcoma cancer cell invasion and metastasis in vivo." (PMID 36268513, 2022).
hepatocellular carcinoma (1 paper, 2022). A malignant tumor that arises from hepatocytes. "Increased abundance of SLC2A5 is also associated with reduced survival in pancreatic adenocarcinoma and hepatocellular carcinoma." (PMID 36268513, 2022).
hypothyroidism (1 paper, 2025). Abnormally low levels of thyroid hormone. "The effect of treatment (hypothyroidism) was significant for Slc27a4, Npc1l1, Slc2a2 and Slc2a5." (PMID 39958687, 2025).
intestinal tumors (1 paper, 2020). "SLC2A5 expression was increased in intestinal tumors of Apc–/– mice compared to wild-type intestinal epithelial cells while fructose levels in the serum and liver were reduced indicating enhanced uptake by the cancer cells." (PMID 32733884, 2020).
leiomyoma (1 paper, 2017). A well-circumscribed benign smooth muscle neoplasm characterized by the presence of spindle cells with cigar-shaped nuclei, interlacing fascicles, and a whorled pattern. "We were also able to confirm that levels of DARC (P < 0.05), SLC2A5 (P < 0.05), ID3 (P < 0.02), LRNF5 (P < 0.01), UGT8 (P = 0.04), ESR1 (P < 0.01), and PGR (P < 0.01) were significantly lower when luteal phase leiomyomas were compared with proliferative phase leiomyomas." (PMID 28637297, 2017).
lymphoma (1 paper, 2017). A malignant (clonal) proliferation of B- lymphocytes or T- lymphocytes which involves the lymph nodes, bone marrow and/or extranodal sites. "Altered expressions of SLC2A family members have been reported in many types of cancer (liver- SLC2A1, SLC2A2, SLC2A5; pancreas- SLC2A1; breast- SLC2A1, SLC2A2, SLC2A4; stomach- SLC2A2, SLC2A4, SLC2A5, SLC2A14; lymphoma- SLC2A5)." (PMID 28978124, 2017).